CDR2 (cerebellar degeneration related protein 2)
Synonyms: CDR62; Yo
Tractability: PROTAC: ubiquitination databases record sites on it.
Gene: Protein-coding gene on chromosome 16 (22,345,936 to 22,437,165, reverse strand). Ensembl gene ENSG00000140743.
Subcellular location (Human Protein Atlas): Nucleoplasm
Gene Ontology:
Molecular function: protein binding
Cellular component: cytoplasm
Genetic constraint (gnomAD): Loss-of-function variants: 27 observed, 42.38 expected, observed/expected ratio (o/e) 0.64, 90% interval 0.47 to 0.88. The upper end of that interval is the gene's LOEUF score, 0.88, which puts it in group 3 of 6, group 1 being the genes least tolerant of losing a copy. Missense variants: 452 observed, 528.2 expected, observed/expected ratio (o/e) 0.86, 90% interval 0.79 to 0.93. Synonymous variants: 221 observed, 215.63 expected, observed/expected ratio (o/e) 1.02, 90% interval 0.92 to 1.15.
Homologues: Orthologues: chimpanzee CDR2 (99% identical), macaque CDR2 (98% identical), dog CDR2 (92% identical), pig CDR2 (90% identical), mouse Cdr2 (89% identical), guinea pig CDR2 (87% identical), rat Cdr2 (85% identical), tropical clawed frog cdr2 (62% identical), zebrafish cdr2a (45% identical), zebrafish cdr2b (33% identical), Drosophila melanogaster Cen (25% identical). Paralogues in human: CDR2L (43% identical).
Diseases named in the same sentence as CDR2 in open-access papers:
CDR2 is named in the same sentence as 31 diseases in open-access papers, as found by Europe PMC text mining. Sharing a sentence is not in itself a finding about the gene and the disease. The quoted sentences say what the papers report.
ovarian tumors (7 papers, 2010 to 2022). "Cerebellar degeneration related protein 2 (CDR2) is an onconeural protein that is known to be ectopically expressed in breast or ovarian tumors, resulting in the generation of autoantibodies that leads to cerebellar degeneration." (PMID 35401697, 2022). "Since ovarian tumors and nervous tissue share common antigens (e.g., cdr2, NMDAR), autoimmune etiology is a probable mechanism of these neurologic disorders." (PMID 24965744, 2015). "In 13 out of 20 tissues, an antigen cdr2 (also called Yo protein) was detected in both cerebellar neurons and ovarian tumors." (PMID 24965744, 2015). "PCD patients harbor breast or ovarian tumors that ectopically express cdr2, which is normally made in cerebellar Purkinje neurons and brainstem neurons and testes." (PMID 20383333, 2010). "We previously reported that the PCD antigen cdr2 is commonly expressed in gynecologic cancers in more than 50% of ovarian tumors and 22% of breast tumors obtained from the general population of cancer patients." (PMID 20383333, 2010). "Cdr2, also known as Purkinje neuronal protein, is expressed on cells within the cerebellum and is similar to the tumour antigen that is expressed in breast and ovarian tumours for anti-Yo antibody." (PMID 26366356, 2015). "Cdr2 is a tumor antigen expressed in a high percentage of breast and ovarian tumors and is the target of a naturally occurring tumor immune response in patients with paraneoplastic cerebellar degeneration, but little is known of its regulation or function in cancer cells." (PMID 20383333, 2010). "Cdr2 is normally found in only the cytoplasm of brainstem neurons and Purkinje cells, but is aberrantly expressed in 62% of ovarian tumors despite being absent in normal ovarian tissue." (PMID 24167748, 2013).
breast carcinoma (4 papers, 2010 to 2020). "In breast cancer patients with anti-Yo antibodies, which bind to the Cdr2 antigen, an overexpression of human epidermal growth factor receptor 2 (HER2) has been found compared to anti-Ri subjects." (PMID 24575143, 2013). "We obtained similar results (25% reduction, p<0.05) in the MCF7 breast cancer cell line, which also expresses cdr2." (PMID 20383333, 2010). "This cdr2 antigen was also expressed in 2 out of 9 breast cancer specimens as well." (PMID 24965744, 2015).
cerebellar degeneration (3 papers, 2022 to 2025). Degeneration of the cerebellum. "Patients with ovarian cancer (OC) may develop anti‐Yo‐associated paraneoplastic cerebellar degeneration (PCD)—a cerebellar ataxia associated with tumor‐induced autoimmunity against CDR2 and CDR2L proteins." (PMID 39473143, 2024). "Cerebellar degeneration-related protein 2 (CDR2) and CDR2-like (CDR2L), are neuronal cell proteins typically expressed in Purkinje cells (referred to as Yo antigens) and have been implicated in paraneoplastic cerebellar degeneration." (PMID 40416967, 2025).
ovarian carcinoma (3 papers, 2009 to 2022). A malignant neoplasm originating from the surface ovarian epithelium. "The inverse correlation between UQCC1 and CDR2 expression in ovarian cancer (as highlighted by analysis of TCGA data), gives support to our results." (PMID 35120576, 2022). "The detection of anti-cdr2 antibodies in ovarian cancer can be improved by in vitro transcription–translation (ITT) of radiolabelled cdr2 protein and immunoprecipitation assay." (PMID 24965744, 2015). "Cdr2 is involved in the inhibition of c-myc oncoprotein that is widely expressed in many tumors, including ovarian cancer." (PMID 24965744, 2015). "Specific cytotoxic T lymphocytes active against cdr2 antigen expressed by ovarian cancer and Purkinje cells were identified in peripheral blood in patients with PCD." (PMID 24965744, 2015). "However, it has become clear that the HuD antigen, as well as other PND antigens, may be commonly expressed outside of neurons in common cancer types (all small cell lung cancers express HuD, and over half of ovarian cancers express cdr2)." (PMID 19492067, 2009).
Intellectual disability (2 papers, 2012 to 2014). "We also identified three 16p12.1(hg 18) microdeletions involving the EEF2K and CDR2 genes, which have been previously linked to intellectual disability and neuropsychiatric phenotypes." (PMID 25516202, 2014).
small cell lung carcinoma (2 papers, 2009 to 2010). Small cell lung cancer (SCLC) is a highly aggressive malignant neoplasm, accounting for 10-15% of lung cancer cases, characterized byrapid growth, and early metastasis. "Despite the safety of the vaccine here, caution is warranted in extending this approach to patients harboring tumors known to be associated with PND (for example gynecologic tumors expressing the cdr2 or Nova antigens and small cell lung cancers expressing the Hu antigen)." (PMID 20824184, 2010).
Autoimmunity (1 paper, 2023). The occurrence of an immune reaction against the organism's own cells or tissues. "Purkinje cytoplasmic autoantibody type 1 (PCA-1)/anti-Yo autoimmunity is a common high-risk paraneoplastic neurological disorder, traditionally attributed antigenically to cerebellar degeneration–related protein 2 (CDR2), predominantly affecting women with gynecologic or breast adenocarcinoma." (PMID 37841252, 2023).
breast tumor (1 paper, 2010). "Cdr2 is not expressed at high levels outside of the brain and testis, but is expressed in 60% of ovarian and 22% of breast tumors and in many transformed cell lines." (PMID 20383333, 2010).
glioblastoma (1 paper, 2016). The most malignant astrocytic tumor (WHO grade IV). "As another example, cdr2 interacts with a nuclear helix-loop-helix leucine zipper protein, MRG X,52 and coexpression of cdr2 and MRG X prevents MRG X-induced glioblastoma cell death." (PMID 27253404, 2016).
gynecologic cancers (1 paper, 2010). "Our results also suggest specific consequences for cdr2 mitotic expression in gynecologic cancers, and thereby address the paradox of why these tumors express the cdr2 antigen despite the fact that this allows them to be targeted by the immune system." (PMID 20383333, 2010). "Together, these data indicate that the onconeural antigen cdr2 acts during mitosis in cycling cells, at least in part through interactions with c-myc, to regulate a cascade of actions that may present new targeting opportunities in gynecologic cancer." (PMID 20383333, 2010).
Kawasaki disease (1 paper, 2022). A rare inflammatory disease characterized by an acute febrile, systemic, self-limiting, medium-vessel vasculitis primarily affecting children. "In this study, we identified CDR2 as a novel suppressed gene for Kawasaki disease via human transcriptome array analysis and DDX24 associated with CAL formation, which may contribute to further understanding of CAL pathogenesis in KD." (PMID 35204331, 2022). "In this study, we first identified CDR2 as a novel suppressed gene for Kawasaki disease via human transcriptome array analysis, and found DDX24 to be associated with CAL formation—both of which may contribute to further understanding of CAL pathogenesis in KD." (PMID 35204331, 2022).
neuroblastoma (1 paper, 2016). Neuroblastoma (NB) is the most common solid, extracranial childhood tumor. "In a separate study, we found that both Parkin and SIAH bind to cdr2 in HEK293 cells and N2 (N-2 supplement) neuroblastoma (data not shown)." (PMID 27253404, 2016).
Parkinson disease (1 paper, 2016). A progressive degenerative disorder of the central nervous system characterized by loss of dopamine producing neurons in the substantia nigra and the presence of Lewy bodies in the substantia nigra and locus coeruleus. "Because we found that cdr2 is highly expressed in the midbrain, we investigated the role of cdr2 in experimental models of Parkinson's disease (PD)." (PMID 27253404, 2016).
retinal disease (1 paper, 2012). "Based on putative function and/or involvement in retinal disease, we selected 16 genes – Bach2, Cdr2, Dusp12, Esrrb, Gpsm2, Haus1, Kdm5b, Lman1, Lrp11, Lrrc2, Ncoa2, Plekha2, Ppargc1b, Trim36, Wisp1 and Zdhhc14." (PMID 22511886, 2012).
viral infection (1 paper, 2021). "Remarkably, one protein, known to have functions for aiding viral proteins, the Cerebellar Degeneration-related Protein 2 (CDR2) was found in silico to be downregulated suggesting that this could be an immune response of the infected chicken against viral infection." (PMID 34147086, 2021).
tumor (9 papers, 2010 to 2024). "In tumoral pathogenesis, the overexpression of CDR2 causes aberrant sequestration of c-Myc, inhibiting its activity, disrupting mitotic exit, and driving tumour proliferation." (PMID 39795928, 2024). "The underlying mechanisms responsible for these antibodies’ production is thought to be linked to the cerebellar degeneration-related protein 2 (CDR2), a protein usually found in the cerebellum that is ectopically produced by tumour cells." (PMID 38391750, 2024). "CDR2 is expressed in the central nervous system, and its ectopic expression in tumor cells of patients with gynecological malignancies is associated with paraneoplastic cerebellar degeneration." (PMID 35204331, 2022). "Cdr2 expression presumably represses cell proliferation through this mechanism, functioning as a tumor suppressor." (PMID 24965744, 2015). "CDR2 has been shown to act during mitosis in mammalian tumour cells through interactions with c-myc." (PMID 23823982, 2013). "Cdr2 overexpression can down-regulate c-myc-dependent transcription in tumor cells, although how the cytoplasmic cdr2 protein bound nuclear localized c-myc in this setting was unclear." (PMID 20383333, 2010). "Here we find that cdr2 is cell cycle regulated in tumor cells with protein levels peaking in mitosis." (PMID 20383333, 2010). "We have found that the paraneoplastic cerebellar degeneration related antigen cdr2 acts as a mitotic protein in tumor cells." (PMID 20383333, 2010). "To explore these observations further, we analyzed cdr2 expression in tumor cells and discovered that it is cell cycle regulated, with protein levels peaking during mitosis." (PMID 20383333, 2010). "CDR2 mRNA, exclusively expressed in PCD-associated tumours, was assumed to be the sole Yo antigen." (PMID 39795928, 2024). "The pathophysiology of PCD is hypothesized to be from antibodies produced in response to an onconeural antigen; this antigen is the cerebellar degeneration-related protein 2 (CDR2) and is expressed by tumor cells." (PMID 36483902, 2022). "Cerebellar degeneration-related protein 2 (cdr2) is expressed in the central nervous system, and its ectopic expression in tumor cells of patients with gynecological malignancies elicits immune responses by cdr2-specific autoantibodies and T lymphocytes, leading to neurological symptoms." (PMID 27253404, 2016). "Elevated expression of cdr2 in a tumor tissue may lead to immune responses that are also active against nervous tissue." (PMID 24965744, 2015). "Over-expression of cdr2 could explain why PCD appears in neoplasms that have a less aggressive course, since suppressive mechanisms mediated by cdr2 are constitutively more effective." (PMID 24965744, 2015). "We find that inappropriate expression of cdr2 in tumor cells can impact c-myc activity." (PMID 20383333, 2010). "Our findings of a function for cdr2 in tumor cell mitosis, together with its normally restricted tissue expression, suggest that it may serve as a tumor target with potential for a high therapeutic index of action." (PMID 20383333, 2010). "In addition, we have found that cdr2 interacts with c-myc in the cytoplasm of Purkinje neurons and that cdr2 can inhibit c-myc-dependent transcription in tumor cell lines." (PMID 20383333, 2010). "The CDR2 gene is widely transcribed and expressed in immune-privileged sites, such as cerebellar Purkinje neurons, brainstem neurons, and spermatogonia; furthermore, CDR2 is present in normal ovarian tissue and tumour tissue, predominantly within vascular smooth muscle cells." (PMID 39795928, 2024). "Our findings of a functional interaction between cdr2 and c-myc in mitosis, together with the fact that cdr2 is expressed in gynecologic and renal tumors raised the question whether cdr2 can promote tumor growth." (PMID 20383333, 2010). "Although we do not see enhanced tumor growth mediated by cdr2 in EL4 tumor cells, a random screen for focus-forming genes in NIH3T3 cells categorized cdr2 as “moderately” oncogenic." (PMID 20383333, 2010).
tumor (continued). "To evaluate whether cdr2 overexpression has growth-promoting activity in vivo, we injected parent EL4 and EC2-1 cells into the flanks of nude mice and monitored tumor growth over the course of two weeks." (PMID 20383333, 2010). "While we did not observe any significant differences in tumor growth rate nor in tumor size before animals were sacrificed, the cdr2 positive EC2-1 derived tumors exhibited a significant increase in the number of mitotic figures compared to that of the EL4 cell-derived tumors." (PMID 20383333, 2010).
cancer (3 papers, 2009 to 2024). A tumor composed of atypical neoplastic, often pleomorphic cells that invade other tissues. "In contrast, CDR2 was primarily localized in the nuclei of neuronal cells, where Yo antibody staining was absent; in contrast, when looking at human cancer cell lines, a strong nuclear staining of CDR2 was noted, along with some cytoplasmic staining." (PMID 39795928, 2024).
neurodegenerative disease (1 paper, 2016). A disorder of the central nervous system characterized by gradual and progressive loss of neural tissue and neurologic function. "However, little is known about the regulation and function of cdr2 in neurodegenerative diseases." (PMID 27253404, 2016).
CDR2 also shares sentences with these, for which no sentence is quoted: Alzheimer disease (1 paper); amyotrophic lateral sclerosis (1); breast adenocarcinoma (1); glioma (1); gynecologic tumors (1); ischemic stroke (1); major depression (1); neurogenetic diseases (1); neurologic disorders (1); paraneoplastic cerebellar degeneration (1); paraneoplastic neurologic syndrome (1); vulvovaginal candidiasis (1); vulvovaginitis (1).